EPCAM (epithelial cell adhesion molecule)
Diseases named in the same sentence as EPCAM in open-access papers (continued):
Sharing a sentence is not in itself a finding about the gene and the disease.
cancer (continued). "Taken together, soluble EpCAM in ascites appears to be a predictor of poor survival in cancer patients with malignant ascites possibly due to the neutralization effect on catumaxomab." (PMID 26296970, 2015). "OCAb9-1 was unable to induce cancer cell apoptosis; we therefore attempted to develop pro-apoptotic antibodies by generating a monoclonal antibody against EpCAM." (PMID 26317650, 2015). "So far, several strategies have been deployed to treat cancer using EpCAM targeting, including diabodies, MAb, and trifunctional antibodies, with the most well-known being Catumaxomab, Edrecolomab, and Adecatumumab, but so far, the results are disappointing." (PMID 25477371, 2015). "Recently, survivin promoter, human telomerase reverse transcriptase promoter and epithelial cell adhesion molecule (EpCAM) promoter have been assayed to delivery TK or CD (cytosine deaminase) genes in cancer cells." (PMID 26053394, 2015). "Several anti-EpCAM antibodies such as edrecolomab and adecatumumab were generated to target cancer and studied in clinical trials." (PMID 26176230, 2015). "The first mAb ever used in human cancer therapy was a murine IgG2a antibody (Edrecolomab; Panorex; mAb 17-1A) directed against EpCAM." (PMID 26317650, 2015). "EpCAM can be downregulated by cancer stem cells in the procedure of epithelial mesenchymal transition." (PMID 26098665, 2015). "Our study confirms that the IsoFlux system harvests many more cancer cells with epithelial features than CellSearch using EpCAM antibodies." (PMID 26397728, 2015). "Currently, CTC isolation is still mainly based on EpCAM expression on epithelial origin cancer cells." (PMID 26397728, 2015). "A number of cell surface markers, such as CD34, CD133, CD24, CD44, CD166, and epithelial cell adhesion molecule (EpCAM), are used to identify and enrich CSCs from several types of cancer." (PMID 26369565, 2015). "Low EpCAM expression or EpCAM downregulation in CTCs have been cited as reasons for the inefficiency of EpCAM capture methods in certain cancer types." (PMID 25944336, 2015). "It was recently demonstrated that the release of EpICD from EpCAM triggers proliferation- and stemness-enhancing signaling in cancer cells." (PMID 26317650, 2015). "Here, we used AMG 110, a well characterized EpCAM/CD3-bispecific BiTE® antibody construct that is clinically being tested in late-stage cancer patients with different carcinomas." (PMID 26510188, 2015). "Our results revealed that EpApt-siEp potentially eradicated EpCAM positive cancer cells through CSC marker suppression and apoptosis, while sparing normal EpCAM negative adjacent cells." (PMID 26176230, 2015). "On the day33, the mice were euthanized and the tumors were excised followed by analysis of the expression of EpCAM and cancer stem cell markers, apoptotic makers and drug resistant proteins were carried out." (PMID 26176230, 2015). "The epithelial cell adhesion molecule (EpCAM) is closely correlated with the occurrence and development of various cancers of epithelial origin." (PMID 26687301, 2015). "Most patients that participated in catumaxomab studies were tested for membrane-bound EpCAM-positive cancer cells in ascitic fluid." (PMID 26296970, 2015). "Both methylation of DNA at cytosine residues within CpG islands as well as trimethylation of lysine residues of histone 3 have been reported to impact the transcription of the EPCAM gene in cancer and human embryonic stem cells, respectively." (PMID 25477371, 2015). "A CAR targeting the pan-cancer antigen “Epithelial cell adhesion molecule” (EpCam) was successfully tested in NK-92 cells." (PMID 25729364, 2015). "From more than 3,000 hybridoma clones, we identified 49 anti-EpCAM mAbs, five of which possessed high binding activity to several human cancer cell lines (SAS, NPC, HCT116, H441, MCF7, BxPC-3, and SKOV-3), but not normal cell lines (HUVECs and NNM)." (PMID 26317650, 2015).
cancer (continued). "EpCAM is considered as an ideal therapeutic target to treat cancer because of the difference in its spatial distribution between normal and cancer cells." (PMID 26176230, 2015). "In the simulations, we focused only on CD44, CD47 and MET overexpressions and underexpressions (excluding EPCAM) because we are considering the cancer cells that are already in the blood vessels." (PMID 25978366, 2015). "This was accompanied by a higher EpCAM protein expression as central adhesion molecule in cancer progression." (PMID 26103567, 2015). "For 20 cases, series specimens containing normal, borderline, cancer nest and metastatic tissue from the same patient were collected and probed by EpCAM aptamer SYL3C-CY3 and random sequences." (PMID 26687301, 2015). "Here, we report that employing EpCAM aptamer (EpApt) and EpCAM siRNA (SiEp) dual approach, for the targeted delivery of siRNA to EpCAM positive cancer cells, efficiently inhibits cancer cell proliferation." (PMID 25576037, 2015). "Heterogeneous expression of EpCAM on cancer cells among different tissue or even within the same sample was observed." (PMID 26718583, 2015). "For example, PLEC, ANXA10, EHF, SLC4A, and CUL4A are expressed at high levels in MDA-MB-231 relative to MCF-7 cells, and MAGED1, SYK, and EPCAM are expressed at higher levels in triple-negative cancer tissues relative to non-invasive control tissues." (PMID 26053433, 2015). "EpCAM has been shown to be overexpressed in cancer initiating cells or cancer progenitor/stem cells (CPC/CSCs)." (PMID 26176230, 2015). "The most common methods for enumerating CTCs are based on the expression of epithelial cell markers (such as epithelial cell adhesion molecule; EpCAM) on cancer cells and antibody-based capture and selection." (PMID 26247814, 2015). "In this study, we developed a monoclonal antibody targeting EpCAM signaling and inhibiting EpICD activation in cancer cells." (PMID 26317650, 2015). "In the extravasation process, EPCAM helps cancer cells in exiting the circulatory system, by inducing the anchorage between CTCs and the vascular endothelium." (PMID 25978366, 2015). "In line with these somewhat conflicting clinical data, the in vitro effects of EpCAM on the behaviour of cancer cells seem to depend on the cancer phenotype and subtypes, suggesting that the molecular role of EpCAM is context-dependent." (PMID 26296970, 2015). "EpCAM is an attractive target for cancer therapy and the EpCAM-specific antibody catumaxomab has been used for intraperitoneal treatment of EpCAM-positive cancer patients with malignant ascites." (PMID 26296970, 2015). "In this study, we developed a new adoptive immunotherapy that targets cancer stem cell antigen, epithelial cell adhesion molecule (EpCAM)." (PMID 25636521, 2015). "Most CTC-identifying assays use antibodies against epithelial markers, e.g. EpCAM, the epithelial cell adhesion molecule that is known to be expressed on many carcinomas including MCC." (PMID 26299616, 2015). "EpCAM was reported to participate in the development and progression of diverse carcinomas as well as serve as a marker of prognosis, which triggered the study of EpCAM-target immunotherapy." (PMID 25960617, 2015). "EpCAM is highly expressed in rapidly proliferating carcinomas and plays an important role in the prevention of cell-cell adhesion, cell signaling, migration, proliferation, and differentiation." (PMID 26356670, 2015). "High levels of expression on the cell surface of multiple human carcinomas makes EpCAM an attractive target for immunotherapy." (PMID 26474755, 2015). "Due to limited applications and adverse effects of these antibodies, researchers wish to exploit more effective and EpCAM antibodies with greater potential to treat carcinomas." (PMID 25960617, 2015). "EpCAM (CD326) is expressed by the epithelium of healthy individuals but overexpressed in most carcinomas." (PMID 26103567, 2015).
cancer (continued). "Since EpCAM is a pan-epithelial differentiation antigen that is expressed on almost all carcinomas and most importantly, localizes at the cell surface, it has been an attractive target for therapeutic applications in cancer treatment." (PMID 25477371, 2015). "Since more than 99% of SUM159 cells were CD44+ cells in both monolayer and sphere cultures, we utilized CD24 and EpCAM as additional surface markers to further investigate cancer stem cells." (PMID 25229616, 2014). "Epithelial Cell Adhesion Molecule (EpCAM) is a transmembrane glycoprotein expressed in several human epithelial tissues and frequently overexpressed in cancer, progenitor, and stem cells." (PMID 25265904, 2014). "Enucleated cell debris was among the events sorted by FACS, but IF confirmed the identity of DAPI+/EpCAM+/CD45- cancer cells." (PMID 25424879, 2014). "CD90 was also found to be variably expressed on the EpCAM+ cancer cells, and thus must be used in combination with EpCAM to cleanly distinguish the stromal fibroblast population." (PMID 25170899, 2014). "This favorable survival data initiated a phase III trial of 258 EpCAM-positive cancer patients with malignant ascites." (PMID 27231556, 2014). "Our study has shown that EpCAM-positive cells were very strongly expressed in the remaining cancer, even when treated by strong anticancer treatment such as HAIC." (PMID 24696843, 2014). "At first, EpCAM was reported as a marker of the cancer stem cell in the pancreatic carcinoma and the breast cancer." (PMID 24696843, 2014). "Based on patterns of coexpression, we identify ten genes as potential candidates for combination therapy with letrozole including EPCAM, a letrozole-induced essential gene and a target to which drugs have already been developed as cancer therapeutics." (PMID 24944582, 2014). "Noteworthy, they used crude MV preparation, without the enrichment for Annexin V positive MVs or for other known MV populations positive for any of the previously discussed cancer markers such as EpCAM." (PMID 25225495, 2014). "Using gene network analysis we selected 3 significantly upregulated cell movement and cancer related genes for further analysis: EPCAM (epithelial cell adhesion molecule), ITGB4 (integrin β4) and PLAU (urokinase-type plasminogen activator (uPA))." (PMID 24885350, 2014). "Catumaxomab was approved in Europe in 2009 for the intraperitoneal treatment of malignant ascites in EpCAM-positive cancer patients, and it is currently in clinical trials in the U.S.." (PMID 27231556, 2014). "In the anaplastic cancer cell lines, EpCAM was strongly expressed at the plasma membrane, and a weak nuclear expression was detected in the cells as well." (PMID 24727741, 2014). "The CD24−/EpCAM+ cancer stem cell subpopulation was markedly increased in sphere culture (12.97±2.95%), which was significantly reduced by CDDO-Im treatment (2.44±0.58%) (p<0.001), an 81.2% inhibition." (PMID 25229616, 2014). "For the target specific methylation, SKOV3 cancer cells, which have an unmethylated EpCAM promoter and active EpCAM expression, were transiently transfected with the chimeric Zinc finger - Dnmt3a catalytic domain (ZF-Dnmt3aCD) constructs." (PMID 24489952, 2014). "In monolayer culture, the CD24−/EpCAM+ cancer stem cell subpopulation was less than 1% (0.16±0.09%), and the subpopulation was not significantly changed by CDDO-Im treatment (0.18±0.04%)." (PMID 25229616, 2014). "Using EpCAM as an additional cell surface marker, CD44+/CD24−/low/EpCAM+ cells were demonstrated to be a more refined subpopulation with cancer stem cell properties, such as higher tumorigenic potential, self-renewal ability and tumorsphere formation." (PMID 25229616, 2014). "EpCAM is over-expressed to varying degrees in numerous human carcinomas, cancer-initiating cells, and in progenitor and normal stem cells." (PMID 24489952, 2014).
cancer (continued). "Of these genes, EPCAM stands out because opportunely, several monoclonal antibodies have already been developed against EPCAM as cancer therapeutics, including the well-tolerated, fully humanized version, adecatumumab." (PMID 24944582, 2014). "AFP is expressed in plasma so it cannot be simply compared, but we believe EpCAM serves well as a marker for locating the cancer stem cells." (PMID 24696843, 2014). "One possible mechanism to explain why these important cell populations are missed is due to the fact that EpCAM expression is lost in cancer cells during the epithelial to mesenchymal transition." (PMID 24489774, 2014). "The use of CD90 is an improvement over using EpCAM alone and sorting the EpCAM− subset, as there are EpCAM− cancer cells present in some SOC samples, as previously determined by our group." (PMID 25170899, 2014). "Taken together these studies suggest that the impact of EpCAM expression in human cancers is likely to be context dependent." (PMID 25265904, 2014). "Although, anti-EpCAM monoclonal antibodies provide protection against cancer, the antibody dependent cytotoxicity relies on the CH2 domain of the antibody that varies significantly from batch to batch during antibody production." (PMID 24489952, 2014). "TACSTD1 (also known as Trop1 or EpCAM) was originally identified as a marker for epithelial carcinomas due to aberrant expression in various tumors." (PMID 25202389, 2014). "Here, we further developed this targeted approach by evaluating the selective delivery of sCD40L to the well-established carcinoma marker EpCAM and the B-cell leukemia marker CD20." (PMID 24741998, 2014). "Targeted delivery of CD40L to the carcinoma marker EpCAM on carcinoma cells induced dose-dependent paracrine maturation of DCs ~20-fold more effective than a non-targeted control scFv:CD40L fusion protein." (PMID 24741998, 2014). "We thus first confirmed the positivity for EpCAM expression in the corresponding primary carcinomas of a representative sample of patients included in the study." (PMID 25261936, 2014). "One possible explanation for this is that mutations in the components of the mTOR pathway, which have been identified in many cancers and cancer cell lines, mask the effect of metformin in EpCAM+ Huh1 cells." (PMID 23922888, 2013). "The mechanism of the effects of BCAA treatment on EpCAM-positive cells was evaluated by accelerated differentiation to cancer cells via activation of mTORC1." (PMID 24312415, 2013). "The third gene, epithelial cell adhesion molecule (EpCAM) is a membrane protein with proto-oncogenic properties that is expressed in numerous cancers and is a promising anticancer drug target." (PMID 23555683, 2013). "One such promoter is epithelial glycoprotein-2/EpCAM/17-1A (EGP2) promoter which selectively kills the EpCAM over expressing cells in many cancers by restricted expression of TK (thymidine kinase) followed by Ganciclovir (GCV) treatment." (PMID 24391761, 2013). "Having confirmed the sensitivity of our aptamers on a range of human cancer cell lines expressing variable levels of EpCAM, we sought to determine the specificity of our aptamers." (PMID 23460885, 2013). "Cancer stem cells with a high EpCAM expression are considered to be more malignant and more prone to give metastasis than those with a low expression." (PMID 23758908, 2013). "Previously, EpCAM was identified as an additional marker of cancer-initiating cells and it was detected in the cytoplasm of hepatic stem cells and in the plasma membranes of hepatoblasts." (PMID 23251255, 2013). "In healthy tissues EPCAM is located in the basolateral membrane but in cancer tissues this protein is homogeneously distributed on the cell surface." (PMID 23938213, 2013). "High EPCAM protein expression was detected in 247 (41.1%) tumors, EPCAM was localized mainly in the cytoplasm of primary cancer cells." (PMID 24422715, 2013).
cancer (continued). "Using either anti-EpCAM or anti-vaccinia specific antibodies, around 5% of all cells were found to be EpCAM-positive three days after treatment, and only around 5–10% of these cancer cells were VACV positive at the same time point." (PMID 24019862, 2013). "Catumaxomab, the first anti-EpCAM antibody, was approved in 2009 for the treatment of malignant ascites in cancer patients with EpCAM positive tumors." (PMID 24380380, 2013). "In contrast, four days later (i.e. 7 days after treatment), less than 2% of all ascitic cells were still EpCAM-positive, and more than 90% of these cancer cells were VACV positive." (PMID 24019862, 2013). "One of the novel contributions of this study was the finding that cancer cells experienced increased sensitivity to chemotherapy agents after EpCAM-positive cells differentiated by BCAA treatment via mTORC1 activation." (PMID 24312415, 2013). "This was the first study that described the cumulative cancer risks and cancer profile of EPCAM deletion carriers." (PMID 23938213, 2013). "EpCAM/CD326 is a type I trans membrane glycoprotein which is expressed in apical membrane of cancer cells and shows baso-lateral expression in normal epithelial cells." (PMID 24391761, 2013). "Epithelial cell adhesion molecule EpCAM is a transmembrane glycoprotein, which is highly and frequently expressed in carcinomas and (cancer-)stem cells, and which plays an important role in the regulation of stem cell pluripotency." (PMID 24009667, 2013). "To regulate the leaky EpCAM promoter expression in the normal tissue we employed the strategy of using miRNA targets that are cancer tissue specific at the downstream of the HSV-TK suicide gene." (PMID 24391761, 2013). "Some of the upregulated genes are related to CSC/’cancer stemness’ such as CXCR4, CD133, EPCAM and SOX9, while others are associated with apoptosis (FASLG, TJP2, DUSP4), the MAPK pathway (MAP2K4, DUSP4), and chemoresistance (MMP1, an ETS1 target gene)." (PMID 24069258, 2013). "The detection of EpCAM on the surface of cancer cells is becoming increasingly important with the advent of anti-EpCAM immunotherapy." (PMID 23460885, 2013). "Two-color immunofluorescent staining for CD44 and EpCAM confirmed both cancer stem cell markers co-expressed in the serial section of CLC." (PMID 23192764, 2013). "To investigate the role of EpCAM in cancer initiation, we examined its expression in hepatic cells at various stages of differentiation." (PMID 23251255, 2013). "A population of CTCs from patients with primary luminal cancer (expressing EPCAM, CD44, CD47 and MET) generated multi-site metastases when injected into mice." (PMID 24286369, 2013). "Epithelial cell adhesion molecule (EPCAM) is overexpressed in most solid cancers and it has recently been identified as a cancer stem cell marker." (PMID 24422715, 2013). "This study contributes to cancer research by clarifying EpCAM expression in hepatic tumors and during the early stages of hepatocarcinogenesis." (PMID 23251255, 2013). "As a putative stem cell marker, the epithelial cell adhesion molecule (EpCAM) is a membrane glycoprotein highly expressed on the majority of cancer cells, although it is also expressed on the majority of normal epithelial cells." (PMID 23251255, 2013). "Recent studies have shown that EpCAM is a biomarker for HpSCs and that EpCAM-positive HCC cells have stem cell features, indicating that EpCAM is one of the cancer stem cell markers of HCC." (PMID 23192764, 2013). "The epithelial cell adhesion molecule (EPCAM) is a glycoprotein of approximately 40 kD that was originally identified as a marker for carcinoma." (PMID 24422715, 2013). "Strong EpCAM expression was restricted to the two carcinomas, while hemangiopericytoma cells were the only displaying CD34+hi expression; both groups of tumors systematically lacked CD45, B- and T-cell markers." (PMID 23472067, 2013).